CD200R1 (CD200 receptor 1)
Description:
Inhibitory receptor for the CD200/OX2 cell surface glycoprotein. Limits inflammation by inhibiting the expression of pro-inflammatory molecules including TNF, interferons, and inducible nitric oxide synthase (iNOS) in response to selected stimuli. Also binds to HHV-8 K14 viral CD200 homolog with identical affinity and kinetics as the host CD200.
Synonyms: CD200R; MOX2R; OX2R; HCRTR2
Tractability: Antibody: its Gene Ontology location is reachable by antibodies, with high confidence; UniProt places it where antibodies can reach, with medium confidence; UniProt predicts a signal peptide or a membrane-spanning region; the Human Protein Atlas places it where antibodies can reach.
Gene: Protein-coding gene on chromosome 3 (112,921,205 to 112,975,103, reverse strand). Ensembl gene ENSG00000163606.
Subcellular location: Cell membrane (Isoform 1); Cell membrane (Isoform 4); Secreted (Isoform 2); Secreted (Isoform 3)
Subcellular location (Human Protein Atlas): Plasma membrane
Pathways (Reactome):
Immune System: Immunoregulatory interactions between a Lymphoid and a non-Lymphoid cell
Gene Ontology:
Molecular function: protein binding; glycosylated region protein binding; immunoglobulin receptor activity; signaling receptor activity
Biological process: heterotypic cell-cell adhesion; intracellular signal transduction; negative regulation of interleukin-6 production; negative regulation of macrophage migration; negative regulation of neuroinflammatory response; negative regulation of T cell migration; regulation of neuroinflammatory response; signal transduction; Fc receptor signaling pathway
Cellular component: cell surface; plasma membrane; receptor complex; external side of plasma membrane; extracellular region
Genetic constraint (gnomAD): Loss-of-function variants: 13 observed, 18.39 expected, observed/expected ratio (o/e) 0.71, 90% interval 0.46 to 1.12. The upper end of that interval is the gene's LOEUF score, 1.12, which puts it in group 4 of 6, group 1 being the genes least tolerant of losing a copy. Missense variants: 223 observed, 262.06 expected, observed/expected ratio (o/e) 0.85, 90% interval 0.76 to 0.95. Synonymous variants: 82 observed, 95.72 expected, observed/expected ratio (o/e) 0.86, 90% interval 0.72 to 1.03.
Homologues: Orthologues: chimpanzee CD200R1 (98% identical), macaque CD200R1 (91% identical), pig CD200R1 (58% identical), rat Cd200r1 (52% identical), mouse Cd200r1 (51% identical), rat Cd200r1l (41% identical), mouse Cd200r4 (40% identical), mouse Cd200r2 (39% identical), mouse Cd200r3 (28% identical), tropical clawed frog XB5962421 (26% identical), tropical clawed frog cd200r1 (26% identical). Paralogues in human: CD200R1L (52% identical).
Diseases named in the same sentence as CD200R1 in open-access papers:
CD200R1 is named in the same sentence as 155 diseases in open-access papers, as found by Europe PMC text mining. Sharing a sentence is not in itself a finding about the gene and the disease. The quoted sentences say what the papers report.
breast carcinoma (18 papers, 2014 to 2025). "In breast cancer (BC), RNAseq revealed increased expression of transcripts encoding immune regulatory receptors (CD200R1), pro-apoptotic molecules (TNFSF10), and pro-angiogenic factors (HGF and ANGPT1) in BC patients compared to healthy donors." (PMID 36733385, 2022). "For instance, 4THM breast cancer cell growth and invasion were increased in CR200R1KO mice and decreased in mice over-expressing CD200, with a lack of CD200R1 expression related to decreased CD8+ and CD3+CD25+ T cells." (PMID 32635224, 2020).
Stroke (17 papers, 2019 to 2025). Sudden impairment of blood flow to a part of the brain due to occlusion or rupture of an artery to the brain. "For instance, interacting OX-2 membrane glycoprotein (CD200) and Cell surface glycoprotein CD200 receptor 1, both associated to acute stroke severity and neurological outcome in the present study are involved in post-stroke inflammation." (PMID 36418382, 2022). "In this study, we investigated the role of CD200R1-mediated signaling in stroke using CD200 receptor 1-deficient mice." (PMID 30777093, 2019). "By using CD200R1-deficient mice, we demonstrate that immune inhibitory signaling is essential for survival following moderate-to-severe stroke." (PMID 30777093, 2019). "Loss of CD200R1 led to high mortality, increased rates of post-stroke infection, and enhanced entry of peripheral leukocytes into the brain after ischemia, with no increase in infarct size." (PMID 30777093, 2019). "The relative protein expression levels of TNF-α and IL-1β were significantly lower in CD200R1-deficient monocytes after stroke compared to WT controls (p ≤ 0.01 and p ≤ 0.05, respectively)." (PMID 30777093, 2019). "Surprisingly, at 72 h after stroke, more deaths occurred in the CD200R1-deficient mice group because of monocyte infiltration and exacerbated microgliosis." (PMID 31440137, 2019). "Next, we examined whether the increased behavioral deficits seen in CD200R1-KO mice at day 7 after stroke were associated with persistent neuroinflammation." (PMID 30777093, 2019). "In this study, the results showed that the dynamics of CD200 and CD200R1 expression present mismatches 7 days after stroke." (PMID 33067924, 2020). "In this study, the expression of CD200 and CD200R1 was altered at early phases in the ischemic penumbra of stroke mouse brains." (PMID 33067924, 2020). "In this study, we observed the expression of CD200 and CD200R1 on infiltrating lymphocytes in the brain after stroke and the diversity of the neuroinflammatory response in acute stroke." (PMID 33067924, 2020). "First, CD200 was expressed in ischemic neurons, and the expression of CD200R1 was in lymphocytes located in the ischemic brain after stroke." (PMID 33067924, 2020). "CD200 was highly expressed in the early stage and then decreased 7 days after stroke onset, whereas the expression of CD200R1 increased over time." (PMID 33067924, 2020). "The level of anti‐inflammatory factors increased and the proinflammatory factors decreased with increasing CD200R1 expression on lymphocytes in the stroke brain." (PMID 33067924, 2020). "One recent study argued that CD200R1 expressed on lymphocytes uniquely impacted monocyte responses, which migrated into the stroke brain from peripheral blood, to regulate the resolution of neuroinflammation in the stroke brain." (PMID 33067924, 2020). "Our study has identified activated peripheral immune cells as the predominant CD200R1 expressers in stroke, providing new cellular targets for systemically administered CD200 supplementation therapies." (PMID 30777093, 2019). "Consistent with the notion of secondary bacterial infection, CD200R1-KO exhibited prolonged lymphopenia at day 7 after stroke." (PMID 30777093, 2019). "Most strikingly, we observed a 52% survival rate for CD200R1-KO mice by day 7 after stroke, significantly lower than was seen for WT controls (83%; p = 0.049)." (PMID 30777093, 2019). "CD200R1-KO mice showed a significant reduction in nesting activity 1 week after stroke as compared to WT controls (p ≤ 0.05)." (PMID 30777093, 2019). "Our data, however, also suggests a significant role for CD200R1 signaling in the peripheral immune compartment following stroke." (PMID 30777093, 2019). "The precipitous functional decline that occurs after day 3 of stroke in surviving CD200R1-KO mice suggests that the peripheral immune state is persistently activated and functionally impaired." (PMID 30777093, 2019).
Stroke (continued). "While the CNS inflammation was resolved by day 7 post-stroke in WT mice, brain-resident microglia and monocyte activation persisted in CD200R1-KO mice, accompanied by a delayed, augmented lymphocyte response." (PMID 30777093, 2019). "The immunohistological analysis confirmed a significant increase in Iba1-positive microglia/macrophages in the striatum of CD200R1-KO mice compared to WT controls at 7 days after stroke (p = 0.045)." (PMID 30777093, 2019). "Importantly, the expression of CD200R1 on infiltrating lymphocytes dictates the survival of mice exposed to brain injury by regulating the post-stroke immune suppression and vulnerability of animals to superinfections." (PMID 36012423, 2022). "However, there are few data available on how the CD200/CD200R1 signaling pathway regulates neuronal inflammation after stroke." (PMID 33067924, 2020). "However, a comprehensive characterization of CD200/CD200R1 regulating the inflammatory response signals in stroke injury is still few." (PMID 33067924, 2020). "Therefore, in this study, we used the CD200R1 agonist CD200Fc to investigate changes in inflammatory cytokines after stroke." (PMID 33067924, 2020). "Within the lymphocyte lineage, CD200R1 is primarily expressed on activated memory T and B cells, indicating that it may play a critical role in the adaptive immune response to stroke." (PMID 30777093, 2019). "As the immune-inhibitory CD200-CD200 receptor 1 (CD200R1) signaling axis is a known regulator of immune homeostasis, we hypothesized that it may play a role in post-stroke immune suppression after stroke." (PMID 30777093, 2019). "Notably, CD200R1-KO mice exhibited a dramatic decrease in body weight following stroke, nearly twice that of WT controls (p = 0.003), which was accompanied by significant dysregulation in body temperature (p ≤ 0.05)." (PMID 30777093, 2019). "Interestingly, nearly all myeloid and lymphocyte subsets were present in higher numbers in CD200R1-KO mice after stroke, suggesting that CD200R1 regulates the amplitude of leukocyte infiltration into the ischemic brain." (PMID 30777093, 2019). "We show for the first time that CD200R1 inhibitory signaling is critical for preventing spontaneous lung infection, attenuating brain inflammation, improving survival, and promoting functional recovery after stroke." (PMID 30777093, 2019). "Indeed, subsequent studies of blood CD4 T cells in CD200R1-KO mice showed a marked re-arrangement in TCRvβ usage at 1 week after stroke, with significantly higher frequency shifts in the subfamily member’s vβ8.1 and 8.2." (PMID 30777093, 2019). "Our observations provide new insights into the contribution of the CD200-CD200R1 inhibitory pathway to the progression of neuroimmune dysfunction following stroke and highlight a novel role for CD200R1 for the prevention of systemic immunosuppression and secondary infection after stroke." (PMID 30777093, 2019). "Therefore, CD200R1 agonists are promising molecules that regulate neuroinflammation development in neurological disease, and CD200R1 might be a potential therapeutic target for the regulation of neuroinflammation in the acute stage of stroke." (PMID 33067924, 2020). "As the day 7 post-stroke period is characterized by the delayed recruitment of T cells, we hypothesized that lymphocyte numbers would be more abundant in the brain of CD200R1-KO mice compared to their WT counterparts." (PMID 30777093, 2019). "Thus, therapeutic targeting of immune inhibitory axes such as the CD200R1 pathway may prove beneficial in reducing secondary infectious complications in already immunocompromised individuals after stroke." (PMID 30777093, 2019). "In light of this, the CD200R1 axis may represent a potential therapeutic target for the treatment of ischemic stroke and other sterile brain injuries, via the suppression of deleterious leukocyte activation and amelioration of stroke-induced lymphopenia." (PMID 30777093, 2019).
Stroke (continued). "CD200R1 is the receptor for CD200 and has been involved in the inhibition of neuroinflammatory pathways in aging, stroke, and multiple sclerosis." (PMID 36012423, 2022). "The peripheral changes in T cell function noted in our study are dramatic, and the high level of CD200R1 expression on these cells, specifically TCR-activated subsets, strongly implicates them in the development of stroke-induced lung infection." (PMID 30777093, 2019). "A recent report has issued that CD200R1 is expressed on infiltrating lymphocytes, not on MG, and CD200R1 KO stroke brains showed higher concentrations of TNF‐α and IL‐1β in ischemic brain tissue of KO mice compared with WT controls at day 7 after stroke." (PMID 33067924, 2020). "In wild-type (WT) animals, CD200R1 was expressed on infiltrating monocytes and lymphocytes after stroke but was absent on microglia." (PMID 30777093, 2019). "Given the lack of CD200R1 expression on microglia before and after stroke, it is likely that the KO response to injury is primarily mediated by peripheral immune cells." (PMID 30777093, 2019). "Emerging data have argued that CD200R1 is mainly expressed on infiltrating monocytes and lymphocytes but is absent on MG after stroke and that CD200R1 expressed in infiltrating lymphocytes is an inhibitory immune receptor in the pathological setting after stroke." (PMID 33067924, 2020). "We only used CD200Fc to enhance CD200R1 expression after stroke, and CD200 or CD200R1 knockout mice were not used to mechanistically study the role of the CD200‐CD200R1 signaling pathway in neuroinflammation induced by ischemic stroke." (PMID 33067924, 2020).
autoimmune disease (16 papers, 2012 to 2025). A disorder resulting from loss of function or tissue destruction of an organ or multiple organs, arising from humoral or cellular immune responses of the individual to their own tissue constituents. "Experimental studies have revealed that CD200/CD200R1 signaling pathway has an immunosuppressive effect on the inflammatory cellular immune response and maintains immune homeostasis in the context of autoimmune diseases." (PMID 34101054, 2021). "CD200fc, a CD200R1 agonist, has been found to have anti-inflammatory effects in neurodegenerative and autoimmune diseases." (PMID 29721190, 2018). "CD200:CD200R1 interaction has been shown to suppress immune responses in autoimmune disorders, infectious diseases, transplantation, and cancer." (PMID 28234914, 2017). "CD200Fc, a CD200R1 agonist, has been found to have anti-inflammatory effects in autoimmune diseases and neuro-degeneration." (PMID 28402258, 2017). "In conclusion, we speculate that CD200/CD200R1 might play a general immunosuppressive role and that CD200-Fc may be of value for the treatment of autoimmune disorders caused by dysfunction of DCs in NZB/WF1 mice." (PMID 27545083, 2016). "CD200/CD200R1 signaling has been suggested to play a role in the induction of autoimmune diseases." (PMID 26690123, 2015). "Consistent with this premise, dysfunction in CD200/CD200R1 signaling has been reported in numerous autoimmune diseases, including Parkinson’s disease, Alzheimer’s disease, rheumatoid arthritis, uveoretinitis, lupus, autoimmune and inflammatory skin disorders and spontaneous fetal loss." (PMID 26690123, 2015). "While available evidence highlighted an important role of CD200/CD200R1 in experimental autoimmune diseases, the role of CD200/CD200R1 in human autoimmune diseases such as SLE remains unknown." (PMID 22621248, 2012).
Alzheimer disease (11 papers, 2011 to 2025). A progressive, neurodegenerative disease characterized by loss of function and death of nerve cells in several areas of the brain leading to loss of cognitive function such as memory and language. "Reduced expressions of CD200 and CD200R1 have been observed in the brains of patients with multiple sclerosis and Alzheimer's disease." (PMID 37391731, 2023). "A decrease in the expression of CD200 and/or CD200R1 has been described in the brain of multiple sclerosis and Alzheimer’s disease patients." (PMID 35296683, 2022). "Alterations in the expression of CD200 and CD200R1 have been described in the brain in multiple sclerosis and Alzheimer’s disease patients." (PMID 33823877, 2021). "A decrease in CD200 and or CD200R1 expression has also been detected in the brain of Alzheimer’s disease and multiple sclerosis patients as well as in an experimental model of multiple sclerosis." (PMID 33823877, 2021). "CD200R1 mRNA expression in Alzheimer’s disease brain sample is low, and IL4 treatment-mediated increase in low basal CD200R1 expression in human microglia is a potential therapeutic strategy." (PMID 34952004, 2022).
Parkinson disease (10 papers, 2011 to 2023). A progressive degenerative disorder of the central nervous system characterized by loss of dopamine producing neurons in the substantia nigra and the presence of Lewy bodies in the substantia nigra and locus coeruleus. "Monocyte-derived macrophages from individuals with Parkinson’s disease show altered CD200R1 regulation in response to inflammatory stimulus." (PMID 37391731, 2023). "MPTP and 6-OHDA-induced models of Parkinson’s disease show decreased CD200R1 expression, higher microglial activation, and increased TNF-α and IL-1β secretion with progressive degeneration of dopaminergic neurons." (PMID 34952004, 2022).
melanoma (9 papers, 2012 to 2025). A malignant, usually aggressive tumor composed of atypical, neoplastic melanocytes. "A previous study using B16 melanoma and J558 plasmacytoma mouse syngeneic models found that CD200 expression could inhibit tumor growth and metastasis by shaping the TME, while another indicated that CD200R1-deficient mice display accelerated CD200+ B16 melanoma growth." (PMID 32635224, 2020).
virus infection (9 papers, 2012 to 2021). "In response to virus infection, Cd200r1 expression was suppressed (lower right), suggesting the CD200-CD200R-mediated suppression of macrophage-like function was inhibited by virus-infection similar to the microglia system." (PMID 32317718, 2020). "Finally, a role for CD200R1 in supporting viral replication was found by comparing elicited peritoneal macrophages and MEFs from CD200R1+/+ and CD200R1−/− mice, in which viral infection was decreased in CD200R1−/− cells." (PMID 23082204, 2012). "Thus, although brain titers of HSV-1 in CD200R1+/+ and CD200R1−/− mice were similar on day 1 post-infection, sustained virus infection was found only in wild type and not in knockout mice." (PMID 23082204, 2012).
glioma (8 papers, 2014 to 2024). A benign or malignant brain and spinal cord tumor that arises from glial cells (astrocytes, oligodendrocytes, ependymal cells). "Moreover, a positive correlation was identified between the risk score and immune checkpoints, namely CTLA4, HVEM, CD200R1, PD-1, and TIM-3, which are implicated in tumor-mediated immunosuppression and evasion, akin to the role of microglia and macrophages in glioma." (PMID 38137116, 2023). "Our study found that several immune checkpoints (BTLA, CD200R1, PD-L1, B7-H3, CD70, CTLA4, IDO1, and PD1) in patients with CDC42 high expression glioma were upregulated compared to the CDC42 low expression group." (PMID 37476838, 2023). "ALKBH5 expression showed positive association with ICP receptors such as TNFRSF14, CD40, CD96 and CD200R1, and ICP ligands such as PDCD1LG2, CD70, TNFSF14, ICOSLG and CD274 in glioma tissues." (PMID 35444654, 2022). "By conducting Pearson correlation analysis on glioma samples from the CGGA and TCGA databases, it was discovered that the expression of SOCS1 is significantly positively correlated with several known inhibitory immune checkpoints, including HVEM, TIM-3, PD-1, PDCD2, TIGIT, CD200R1, CTLA4, and CD47." (PMID 39654174, 2024).
multiple sclerosis (8 papers, 2012 to 2025). A progressive autoimmune disorder affecting the central nervous system resulting in demyelination. "CD200 deficiency or treatment with a CD200R1-blocking antibody resulted in an enhanced pathology in an experimental model of multiple sclerosis, while the administration of a CD200R1 agonist resulted in an attenuated pathology." (PMID 33823877, 2021). "In summary, the CD200-CD200R1 system is a potential therapeutic target in multiple sclerosis, and CD200R1 agonists are molecules that may be worth developing in this context." (PMID 28522962, 2017).